IL18 (interleukin 18)
Diseases named in the same sentence as IL18 in open-access papers (continued):
Sharing a sentence is not in itself a finding about the gene and the disease.
type 1 diabetes (28 papers, 2009 to 2026). "The IL18 (−137G >C) polymorphism is also associated with an increased risk of developing type 1 diabetes in the Egyptian population." (PMID 41257666, 2025). "IL-18 has demonstrated a positive correlation with HbA1c levels in type 1 diabetes, suggesting a potential association between IL-18 and glycemic control in these patients." (PMID 39273664, 2024). "IL-12 and IL-18 are two cytokines that have been shown to exert strong proinflammatory activity and have been implicated in the pathogenesis of type 1 diabetes in mice and humans." (PMID 24677179, 2014). "Significant association has been shown between IL18 and type 1 diabetes, Crohn's disease, atopic eczema, inflammatory bowel disease, and asthma." (PMID 20478055, 2010). "Interleukin-18 (IL-18) is a pro-inflammatory molecule that has been shown to be involved in the susceptibility of several human complex diseases such as immune diseases, type I diabetes and cardiovascular diseases (CVD)." (PMID 19473509, 2009). "The -137 C allele has been associated with adverse outcomes and higher serum IL-18 cytokine levels, and the -607 A allele has been associated with improved outcomes and lower serum IL-18 levels in type 1 diabetes." (PMID 19178691, 2009). "Some authors also linked IL-18 or its receptor polymorphism with type 1 diabetes." (PMID 24677179, 2014). "In the present study, patients with type 1 diabetes had higher serum level of IL-12 and IL-18 in comparison to the healthy subjects from the control group." (PMID 24677179, 2014). "Patients with type 1 diabetes showed statistically higher serum levels of IL-12 and IL-18 than children from the control group." (PMID 24677179, 2014). "Since IL-12 and IL-18 mediate inflammatory response and Tregs exhibit anti-inflammatory potential, we aimed to examine their reciprocal relationship in patients with type 1 diabetes." (PMID 24677179, 2014). "Since IL-12 and IL-18 mediate inflammatory response and Tregs exhibit anti-inflammatory potential, we aimed to examine the relation between them in patients with type 1 diabetes." (PMID 24677179, 2014). "Likewise, disruption of Treg-mediated immunoregulation has been reported in type 1 diabetes, where IL-12 and IL-18 enhance the activity of CTL and NK cells." (PMID 41488664, 2025). "Elevated levels of IL-18 have been reported in individuals with type 1 diabetes." (PMID 39563343, 2024). "Similarly, serum IL-18 levels have also been reported to be elevated in type 1 diabetic patients, half of which had a form of DR." (PMID 32911690, 2020). "With respect to this, an association of the IL18 -137 G>C [rs187238] but not the IL18 -607 C>A (rs1946518) gene polymorphism with susceptibility to type I diabetes was reported in a study." (PMID 20331879, 2010). "Moreover, it modulates the response to interleukin-18, cytokine-mediated signal transduction pathways and immune responses such as T cell-mediated positive regulation of cytotoxicity, which has a significant effect on type I diabetes." (PMID 30521536, 2018). "IL-18 can promote IFN-γ secretion, which is one of the most important mechanisms of type 1 diabetes (T1D)." (PMID 31427887, 2019). "In the current study, we aimed to investigate possible associations between gut related inflammatory biomarkers including LBP, CD14, TLR4, I-FABP and IL-18 and the presence of CAD and with established CHD, in patients with long-term type 1 diabetes compared to a control group." (PMID 39563343, 2024). "The levels of anti-inflammatory (IL-35, IL-10, IL-4) and proinflammatory (TNF-α, IL-12, IL-18) cytokines were statistically comparable between the type 1 diabetes patients with Hashimoto’s disease and those without." (PMID 39273664, 2024). "However, the results of our analysis lead us to conclude that patients with type 1 diabetes have enhanced inflammatory response, which is manifested by increased values of CRP, HbA1c, IL-12, and IL-18." (PMID 24677179, 2014).
lymphoma (27 papers, 2015 to 2025). A malignant (clonal) proliferation of B- lymphocytes or T- lymphocytes which involves the lymph nodes, bone marrow and/or extranodal sites. "Specifically, the alleles responsible for this increased susceptibility to lymphoma development were the “G” in IL-18 (rs1946518) and the allele “ins” in NFκB-94 ins/del (rs28362491)." (PMID 38397043, 2024). "Both IL-18 (rs1946518)(χ2 = 136.0579, P < 0.0001) and NFκB 94 ins/del (rs28362491) (χ2 = 6.1462, P = 0.0463) resulted to be significantly associated with lymphoma." (PMID 29312552, 2017). "We found that IL-18 (rs1946518) and NFκB94 ins/del (rs28362491) contributed to lymphoma susceptibility and allele G in IL-18 was significantly associated with the risk of lymphoma." (PMID 29312552, 2017). "In the present study we found the polymorphism of IL-18 (rs1946518) was significantly associated with lymphoma susceptibility and GG genotype in IL-18 is significantly associated with the risk of lymphoma." (PMID 29312552, 2017). "We also found that the allele “G” of IL-18 (rs1946518) showed a significantly increased risk of lymphoma." (PMID 29312552, 2017). "IL-18 has been linked to the severity of SS, inflammation, parotid-gland enlargement, and lymphoma, while IL-23 appears to promote differentiation of Th17 cells." (PMID 34630072, 2021). "Thus, SS-1 may regulate IL-18 and IL-23 levels, decreasing the risk of lymphoma, inflammation, and Th17-cell differentiation." (PMID 34630072, 2021). "In the present study, a reduced expression of IL18 in MDV-infected BMDMs of the susceptible line might lead to decreased NK cell activity which in turn may play a role in formation of lymphomas in these birds, as a higher NK activity is more likely to be involved in antitumor responses." (PMID 30678299, 2019). "Therefore, our results suggested that IL-18 (rs1946518) polymorphism may be an unfavorable factor that increases the susceptibility to lymphoma." (PMID 29312552, 2017). "An innovative approach is armored CAR-T cells engineered to secrete IL-18 (huCART19-IL18), which demonstrated robust expansion, acceptable safety, and durable clinical responses in relapsed/refractory lymphoma." (PMID 41200171, 2025). "In studies on the effect of IL-18 on the anti-CD20 mAb-mediated regression of non-Hodgkin lymphoma, it was demonstrated that IL-18 synergized with the mAb in the lymphoma regression." (PMID 38247820, 2024). "It has been shown that the NLRP3 inflammasome regulates PD-L1 and immune cells to promote immunosuppression, while IL-18 negatively impacts anti-lymphoma immunity in vivo." (PMID 38177104, 2024). "Several studies assessed IL-18 mRNA and protein expression in lymphoma patients either in serum or the affected tissues." (PMID 38397043, 2024). "Preclinical studies showed that IL-18 plus ofatumumab was more effective than IL-18 plus rituximab in a lymphoma xenograft model." (PMID 35529882, 2022). "Remarkably, in vivo administration of the NLRP3 inhibitor, MCC950, repressed lymphoma expansion and reduced the concentrations of IL-1β and IL-18, consequently downregulating PD-L1." (PMID 35897704, 2022). "Preclinical models and phase 1 trials established efficacy and biological activity of IL-18 against solid tumors and lymphoma." (PMID 35529882, 2022). "Our previous study found IL-18 mRNA expression and plasma IL-18 level were increased in lymphoma patients." (PMID 34211462, 2021). "It was demonstrated that combination of IL-12/IL-18/IL-15-preactivated NK cells persisted at high cell numbers with potent effector function in lymphoma and melanoma tumor models in human and mice." (PMID 34768814, 2021). "NLRP3 inflammasome can induce the anti-dexamethasone effect of lymphoma cells through IL-18, thereby inhibiting apoptosis and promoting tumor proliferation." (PMID 34805183, 2021).
lymphoma (continued). "Thirty-five sample-matched newly-diagnosed lymphoma patients were included to explore the relationship between IL-18 genotype and its expression." (PMID 29312552, 2017). "We also demonstrated that plasma IL-18 level among lymphoma patients carrying GT genotype was higher than those carrying the GG genotype." (PMID 29312552, 2017). "Accordingly, plasma IL-18 level was also significantly elevated in newly-diagnosed lymphoma patients than in controls (p < 0.0001), and decreased after chemotherapy remission in the paired 11 patients (p = 0.0098)." (PMID 29312552, 2017). "As IL-18 plays an extremely important role in the pathogenesis and development of lymphoma, we used IL-18 and its neutralizing antibody to further investigate its mechanism." (PMID 29312552, 2017). "The mRNA and plasma expression levels of IL-18 were significantly elevated in primary lymphoma patients and decreased after remission." (PMID 29312552, 2017). "In conclusion, NLRP3 inflammasome contributes to the susceptibility and plays a carcinogenic role through its effector cytokine IL-18 in lymphoma." (PMID 29312552, 2017). "In patients with SS-associated MALT lymphomas, increased IL-18 mRNA levels in affected SGs were documented compared to SS patients without lymphoma, with higher IL-18 also correlating with the presence of GC-like structures." (PMID 38397043, 2024). "Additionally, samples from newly diagnosed lymphoma patients showed significantly elevated mRNA levels of the IL-18 cytokine, the effector of the inflammasome pathway, compared with controls." (PMID 35897704, 2022). "Moreover, IL-18 promoted proliferation, inhibited apoptosis and reduced the anti-tumor effect of dexamethasone for lymphoma cells." (PMID 34211462, 2021). "A previous study demonstrated that activated NLRP3 increases IL-18 in patients with lymphoma." (PMID 33096896, 2020). "In addition, NLRP3 inflammasome increases IL-18 and IL-1β production, thereby promoting tumor cell proliferation and inhibiting apoptosis during lymphoma development." (PMID 32063899, 2019). "To study the expression profile of IL-18 in lymphoma patients, we selected 68 sample-available lymphoma patients including 46 newly-diagnosed patients and 22 relieved patients and 40 controls for mRNA detection by RT-PCR and 35 lymphoma patients and 15 controls for plasma detection by ELISA." (PMID 29312552, 2017). "This suggested that IL-18 was highly expressed in lymphoma patients." (PMID 29312552, 2017). "We further investigated the expression of IL-18 in lymphoma patients, and found that the mRNA and plasma expression levels of IL-18 in newly-diagnosed lymphoma patients were significantly higher than controls, and decreased significantly after chemotherapy remission." (PMID 29312552, 2017). "We have demonstrated the elevated IL-18 in lymphoma patients was decreased after remission and activated NLRP3 inflammasome could induce higher IL-18." (PMID 29312552, 2017). "Assuming that high levels of IL-18 are beneficial in cancer or lymphoma, respectively, human recombinant IL-18 (SB-485232) was administered in combination with rituximab in a phase 1 study to patients with non-Hodgkin's lymphoma (NHL) revealing a response rate of 26%." (PMID 27294147, 2016). "IL-18 mRNA and protein levels are significantly higher in newly diagnosed lymphoma patients compared to healthy controls (p = 0.0288 and p < 0.0001, respectively), showing a decrease in patients that achieve lymphoma remission after chemotherapy (p = 0.0366 and p = 0.0098, respectively)." (PMID 38397043, 2024).
lymphoma (continued). "Considering that either NLRP3 or IL-18 inhibition in lymphoma mouse models leads to a decrease in PD-1/TIM-3-expressing T-cells, MDSCs, tumor-associated macrophages, and regulatory T-cells, it can be proposed that IL-18 mediates the accumulation of immunosuppressive cell populations." (PMID 38397043, 2024). "Essentially, mRNA levels of NLRP3, IL-1β, IL-18, caspase-1, and P2 × 7R, components of the NLRP3 inflammasome, were significantly elevated in SjS patients who subsequently developed lymphoma." (PMID 35897704, 2022). "Considering this observation, it can be proposed that IL-18, secreted as a result of NLRP3 inflammasome activation in the setting of lymphoma, can induce signaling pathways promoting lymphomagenesis via its interaction with the IL-18R on lymphoma B-cells." (PMID 38397043, 2024). "Our study found that the expression levels of NLRP3-related genes IL-18, IL-1β, NLRP3 and caspase-1, were increased after addition of ATP plus LPS, suggesting NLRP3 could be primed and activated in lymphoma cells." (PMID 29312552, 2017). "The activation of NLRP3 may increase the expression of NLRP3-related genes such as IL-18, IL-1β, NLRP3 and caspase-1 in lymphoma cells, thereby promoting proliferation, inhibiting apoptosis, and reducing the anti-tumor effect of dexamethasone." (PMID 29312552, 2017). "The lowest doses of hIL-18 given to lymphoma patients resulted in IL-18 plasma levels of > 10 ng/mL and biomarker studies have shown in vivo activation rather than suppression of NK cells during IL-18-based immunotherapy." (PMID 35529882, 2022). "The researchers reported significantly higher mRNA expression for P2X7R, NLRP3, caspase-1, IL-18, and IL-1β in patients with SS who developed MALT-NHL over the follow-up, compared to both SS patients who did not develop lymphoma and controls." (PMID 38397043, 2024).
multiple sclerosis (27 papers, 2010 to 2026). A progressive autoimmune disorder affecting the central nervous system resulting in demyelination. "Another enriched pathway that IL-18 is involved in is the “role of IFN-beta in inhibition of Th1 cell differentiation in multiple sclerosis”." (PMID 36816031, 2023). "In multiple sclerosis, caspase-1, IL-18, and IL-1β are positively regulated in PBMCs and in mononuclear cells in the CSF during disease development, and caspase-1 expression is upregulated in demyelinating lesions." (PMID 36298702, 2022). "Activation of the NOD-like receptor protein 3 (NLRP3) inflammasome is involved in the maturation and secretion of IL-1β and IL-18 and, thus, plays a key role in the pathogenesis of many inflammatory conditions, including multiple sclerosis (MS)." (PMID 31736980, 2019). "The reduction of MAIT cell frequency was related to the elevated serum concentration of IL-18 in multiple sclerosis." (PMID 28288675, 2017). "Whether suppression of IL-18 will affect IL-17-mediated diseases such as multiple sclerosis or reduce metastatic melanoma will also be determined in clinical trials." (PMID 24115947, 2013). "Using a model for multiple sclerosis termed experimental autoimmune encephalomyelitis (EAE), a role for IL-18 was studied." (PMID 24115947, 2013). "BACE-1 is highly expressed at the time when peripheral nerves become myelinated and is needed for neuregulin processing, with loss of BACE-1 inducing hypomyelination, suggestive of a role for IL-18 and BACE-1 in multiple sclerosis." (PMID 22898493, 2012). "In addition, through GABA-mediated pathways homotaurine has anti-inflammatory and therapeutic properties in a multiple sclerosis animal model, even involving increased IL-10-secreting responses, but unfortunately IL-18 and IL-33 cytokines have not been evaluated in that context." (PMID 35515001, 2022).
Hepatic steatosis (25 papers, 2014 to 2026). Steatosis is a term used to denote lipid accumulation within hepatocytes. "Exogenous IL-18 administration has been shown to counteract steatohepatitis in mice, whereas IL-18-deficient mice exhibit hepatic steatosis and steatohepatitis." (PMID 40243151, 2025). "Its ligand, IL-18, has been associated with hepatic steatosis and elevated liver enzymes in people with HIV infection and has been used as a predictive marker in liver steatosis in obese children." (PMID 37371624, 2023). "High levels of IL-18 also mediated the reduction in hepatic steatosis observed in mice with a conditional deficiency in Src homology-2 domain-containing protein tyrosine phosphatase-2 (SHP2) in macrophages." (PMID 36313762, 2022). "It has been clearly reported that excessive accumulation of fat will increase the concentration of IL‐18 and promote liver cell damage associated with fatty liver." (PMID 33720453, 2021). "Recent studies have implicated IL-18 signaling in hepatic steatosis and fibrosis." (PMID 40243151, 2025). "Obese C57BL/6 mice (naturally harboring the NLRP1b2 allele-resulting in low IL-18 levels) have increased hepatic steatosis when compared to obese NLRP1b1 transgenic C57BL/6 mice or Balb/c mice (naturally harboring the NLRP1b1 allele-resulting in high IL-18 levels)." (PMID 36313762, 2022). "Reduced expression of hepatic inflammatory cytokines (TNF-α, IL-1β, IL-18) and improved hepatic steatosis; decrease in body weight as well." (PMID 40893881, 2025). "NLRP1-/- mice (with low IL-18 levels) spontaneously developed hepatic steatosis, a situation aggravated on HFD." (PMID 36313762, 2022). "The concentration of IL‐18 in the serum of fatty liver patients (911.97; 775.55–1130.03 pg/mL) is higher than that of healthy controls (483.09; 402.52–599.70 pg/mL), and its pathogenesis is more complicated." (PMID 33720453, 2021). "By stimulating Kupffer cells to activate the TLR4 signaling pathway, LPS induces the secretion of TNF-α, IL-1, IL-6, IL-12, and IL-18 in Kupffer cells, thereby triggering hepatic steatosis, IR, and hepatocyte apoptosis, among others." (PMID 34966296, 2021). "The IL‐18 concentration in the serum of patients with liver cancer, hepatitis C, hepatitis B, fatty liver disease, and autoimmune hepatitis was plotted as a ROC curve." (PMID 33720453, 2021). "The IL‐18 serum concentrations of liver cancer, hepatitis C, hepatitis B, and fatty liver disease patients were significantly higher than that of healthy controls." (PMID 33720453, 2021). "Accordingly, IL-18 has been considered to play a role in predicting advanced liver steatosis and fatty liver in obese children." (PMID 33202693, 2020). "In mice on a high-fat diet, IL-18 has previously been identified among the intermediate markers of hepatic steatosis and similar findings have been obtained in early steatosis in rabbits." (PMID 33202693, 2020). "We were able to identify IL-18-dependent signaling as a modulator of early liver damage in fatty liver, preceding development of histologic NASH." (PMID 33202693, 2020). "Serum IL-18 concentration was evaluated in serum of 108 obese children, determined with ELISA, and referred to degree of liver steatosis in USG or total intrahepatic lipid content assessed by magnetic resonance proton spectroscopy (1HMRS)." (PMID 29854715, 2018). "Elevated serum IL-18 concentration and its correlation with hepatocyte injury, systemic inflammation, and degree of liver steatosis support role in NAFLD pathomechanism." (PMID 29854715, 2018). "IL-18 can be considered to play a role in predicting advanced liver steatosis and fatty liver in obese children." (PMID 29854715, 2018). "In this study we were able to demonstrate significant increase of IL-18 serum concentrations with degree of liver steatosis measured using USG." (PMID 29854715, 2018).